TLR4 (toll like receptor 4)
Diseases named in the same sentence as TLR4 in open-access papers (continued):
Sharing a sentence is not in itself a finding about the gene and the disease.
acute kidney injury (continued). "Toll-like receptor 4 (TLR4) is an important pattern recognition receptor mainlyexpressed on renal tubular epithelial cells and vascular endothelial cells thatmediates the nuclear factor (NF)-κB inflammatory cascade andparticipates in the pathogenesis of acute kidney injury (AKI)." (PMID 39076193, 2022). "Both diabetic patients with or without kidney failure and non-diabetic patients with renal failure had increased TLR2 and TLR4 mRNA expression in association with increased levels of proinflammatory cytokines (TNF-α, IFN-γ, and IL-6) compared to normal subjects." (PMID 33442388, 2020). "In addition to HMGB1, histones released from damaged renal cells in acute kidney injury (AKI) triggered neutrophil recruitment and renal inflammation via interaction with TLR2 and TLR4, in turn activating MyD88, NF-κB and mitogen activated protein kinase (MAPK) signaling." (PMID 32731558, 2020). "C3H/HeJ mice with a TLR4 gene deletion do not show LPS-induced acute kidney injury (AKI), whereas mice with a normal TLR4 gene can present severe AKI." (PMID 28805489, 2017). "AQP3, on the other hand, modulates inflammation through the Toll-like receptor 4 (TLR4) pathway, while AQP1 plays a role in immune responses by activating the PI3K pathway, promoting macrophage polarization, and protecting against lipopolysaccharide (LPS)-induced acute kidney injury (AKI)." (PMID 39544938, 2024).
malaria (99 papers, 2007 to 2025). Malaria is a serious and sometimes fatal disease caused by a parasite that commonly infects a certain type of mosquito which feeds on humans. "Both the TLR4-Asp299Gly and the TLR4-Thr399Ile variants confer an increased risk of severe malaria in Ghanaian children, linking these SNPs to disease manifestation." (PMID 41295183, 2025). "Statistically significant evidence was found for the association of TLR4 and related genes with the incidence of clinical malaria (p = 0.0005)." (PMID 37287037, 2023). "In particular, the variations of T in the SNP rs5030719 of TLR4 conferred risk of clinical malaria compared to the G allele." (PMID 37287037, 2023). "TLR4 was the only gene identified to be statistically associated with malaria in both child and maternal analysis as well as producing haplotypes associated with the disease in the HTR analysis." (PMID 37287037, 2023). "An overlapping set of genes, HP, ICAM1, IFNG, TLR2, and TLR4 were found to contain SNPs statistically significantly associated with malaria in both maternal and child analyses." (PMID 37287037, 2023). "TLR4 signaling has been implicated in the pathogenesis of severe malaria including cerebral malaria, and free-heme has been shown to induce TLR4 expression in endothelial cells." (PMID 36618355, 2022). "The current meta-analysis study has systematically evaluated the role of TLR4/9 in severity of malaria or susceptibility to malaria risk in people living in endemic countries." (PMID 34217314, 2021). "The mutant alleles of TLR-4 SNPs seem to have originated in Africa in an environment where malaria appears as a major evolutionary pressure." (PMID 34621380, 2021). "In spite of the obscure nature of the mechanisms for TLR4 polymorphisms, the 399 SNP is suggested to be predispose to severe malaria." (PMID 32944216, 2020). "In malaria endemic populations, single nucleotide polymorphisms (SNPs) within the TLR4 coding and TLR9 promoter regions are associated with variation in disease severity and parasitemia control." (PMID 33013876, 2020). "In the case of pregnancy malaria, primiparous infected mothers with common TLR4 and TLR9 polymorphic variants are correlated with severe complications such as low birth weight and maternal anemia." (PMID 33013876, 2020). "Although the role of TLR2 and TLR4 in malaria remain obscure, TLR9 deficient mice were reported to be resistant to PbA-induced cerebral malaria, indicating a role in pathology of TLR9 rather than cerebral malaria protection." (PMID 32944216, 2020). "On Porto Santo, increasing numbers of T alleles at SNP 5239s1 (estimate = 0.69, SE = 0.27, p = 0.011), and A alleles at SNP TLR4_2 (estimate = 1.03, SE = 0.42, p = 0.016), were associated with increased malaria risk." (PMID 31788192, 2019). "For a common TLR-4 SNP in Ghana, increased susceptibility to severe malaria but a trend towards reduced mortality was found in a previous study." (PMID 30642347, 2019). "TLR4 polymorphisms have also been associated with disease severity, particularly the hyporesponsive polymorphisms Tlr4 Asp299Gly and Tlr4 Thr399Ile which predispose children to severe malaria." (PMID 31178840, 2019). "Various mouse models have illustrated the role of TLR4 in pregnancy associated infections and disorders, including malaria, bacterial infections, lipopolysaccharide exposure and uterine ischemia." (PMID 31178840, 2019). "Present study evaluated the importance of rs4986790 polymorphism of TLR4 gene in susceptibility towards malaria, clinical outcomes of the disease and responsible species of malaria." (PMID 29922617, 2018). "This is the first study which relates the association between rs4986790 polymorphism of TLR4 gene and malaria in the Pakistani population." (PMID 29922617, 2018). "Unexpectedly, we uncovered that the expression of TLR4 in the fetal compartment led to a reduction in the incidence of malaria-induced fetus loss in utero." (PMID 29440369, 2018).
malaria (continued). "Human genetic studies have associated TLR4 polymorphisms with parasitemia levels in patients with mild malaria and with the risks of clinical malaria, severe malaria, maternal anemia, and low birth weight in term infants." (PMID 29440369, 2018). "TLR4 has been associated with clinical malaria outcomes in human studies as its suppression in dendritic cells has been associated with uncomplicated P. falciparum infection in Malian children of the Dogon ethnicity." (PMID 26961973, 2016). "All the genotypes of both TLR4 SNPs were found in the study population with their minor alleles: 299Gly and 399Ile, found to be 17.6 % and 14.7 % in severe malaria children." (PMID 27350800, 2015). "This study determined the association of TLR4 Asp299Gly and Thr399Ile with uncomplicated and severe malaria among Nigerian children of similar ethnic background in Lagos." (PMID 27350800, 2015). "Since the burden of these infectious diseases varies across the various malaria endemic countries, there is thus a high possibility of differences in their contributions to the evolution of mutant variants of TLR4." (PMID 27350800, 2015). "In Brazil, where temporal changes from low to moderate P. vivax and P. falciparum malaria transmission also occur, contradictory findings, regarding the association of TLR4 Asp299Gly polymorphisms with protection from clinical malaria have been reported." (PMID 27350800, 2015). "In this study and under dorminant model of inheritance, the significant association of the two TLR4 SNPs with clinical malaria syndromes such as fever, severe anaemia and high parasite density was found." (PMID 27350800, 2015). "Further stratification of the clinical malaria cases showed that the frequencies of the minor alleles: 299Gly and 399Ile, of these TLR4 SNPs were greater than 10 % (17.6 % and 14.7 % respectively) only in severe malaria children." (PMID 27350800, 2015). "Different studies have shown an association of TLR4 polymorphisms withsusceptibility/resistance to malaria disease." (PMID 23862121, 2013). "Although synergistic effects for TLR2 and TLR4 have been described for tuberculosis, malaria, and lupus, our study is the first to associate a genetic trait for TLR2 and TLR4 SNPs with susceptibility to meningitis." (PMID 23691182, 2013). "It has alsobeen shown that the presence of the TLR4 Gly299Gly/Thr399Thr genotype is associated with an increasein susceptibility to malaria but a reduction inmortality and cerebral malaria in the Ghanaian andCameroonian populations." (PMID 23862121, 2013). "Different studies haveevaluated the association of TLR4 polymorphismswith susceptibility/resistance to differentdiseases including malaria." (PMID 23862121, 2013). "The TLR4 Asp299Gly was associated with an increased risk of maternal anemia and infant low-birth weight in pregnant women with malaria." (PMID 23316245, 2012). "Unlike the results reported here, two studies in Ghana have revealed frequent polymorphisms at TLR4 that conferred an increased risk of severe malaria and clinical manifestations of malaria during pregnancy." (PMID 22615793, 2012). "On the other hand, different reports have also been published for another TLR4 SNP, Thr399Ile, which some authors have associated with severe malaria, whereas others have observed with similar frequency in malaria patients and in healthy individuals." (PMID 22691414, 2012). "tlr-4 polymorphisms are assumed to be correlated with risk of severe malaria as reported by Mockenhaupt and colleagues." (PMID 21457584, 2011). "On the other hand, study by Mockenhaupt and colleagues showed that tlr-4 T399I predisposes to severe malaria with symptoms such as severe anaemia and respiratory distress." (PMID 21457584, 2011). "Polymorphisms in TLR4 are also reported to play a role in controlling the parasitemia level in malaria." (PMID 22096530, 2011).
malaria (continued). "Recently, a polymorphism in the TLR4 gene has been implicated in protection against malaria, while a variant of the TLR2-4 adapter Mal/TIRAP can provide protection against invasive pneumococcal infection, malaria, and TB." (PMID 18575596, 2008). "The origin of the polymorphisms of toll-like receptor 4 (TLR4), +986A/G (Asp299Gly), and +1196C/T (Thr399Ile) investigated in our study is considered to be rooted in Africa due to the selective pressure exerted by malaria." (PMID 39459627, 2024). "This supports the current literature and suggests that further research into the role of TLR4, as well as associated genes, in clinical malaria may provide insight into treatment and drug development." (PMID 37287037, 2023). "By testing for associations with malaria infection and risk at TLR4 and novel malaria‐associated SNPs in divergent populations, we have revealed contrasting patterns of malaria risk and potential local adaptation, potentially due to different patterns of coevolution between the two populations." (PMID 31788192, 2019). "Study of other polymorphisms in the TLR4 gene, association between inflammatory and anti-inflammatory cytokines with rs4986790 genotypes in malaria groups and meta-analysis may investigate the role of rs4986790 polymorphism in the severity of malaria." (PMID 29922617, 2018). "This study considers the hypothesis that polymorphism in TLR4 gene can modulate the disease susceptibility and clinical outcome of malaria." (PMID 29922617, 2018). "Furthermore, T399I and A299G in TLR4 were associated with increased parasitemia in Indian patients with Pf-malaria, indicating that this receptor is important in inducing immune response to malaria." (PMID 28850598, 2017). "In conclusion, our findings suggest that TLR4 Asp299Gly and Thr399Ile polymorphisms among Nigerian children of Yoruba ethnic background may modulate susceptibility to severe malaria and other disease outcomes such as severe anaemia and hyperpyrexia." (PMID 27350800, 2015). "The expression of TLR4 by these populations makes them susceptible to the inflammatory effects of deleterious TLR4 activators TNFα and IFNγ, both of which are up-regulated in malaria." (PMID 26555697, 2015). "Therefore, there is a need for more immunogenetic studies, regarding the role of TLR4 polymorphisms in malaria pathogenesis, particularly in other countries with high malaria transmission." (PMID 27350800, 2015). "It is on this basis that the present study was carried out to determine the frequency, distribution and association of mutant genotypes of TLR4 Asp299Gly and Thr399Ile polymorphisms in a cohort of P. falciparum infected Nigerian children with susceptibility to clinical and severe malaria." (PMID 27350800, 2015). "Differences in the co-segregation patterns of TLR4 Asp299Gly/Thr399Ilegenotypes in the Baluchi population compared to other malaria endemic populations maysuggest different local evolutionary pressure on TLR4 polymorphisms by malaria in thisregion." (PMID 23862121, 2013). "Although common TLR4 mutations have previously been shown to increase the risk of severe malaria in African children, we observe only a marginal susceptibility effect of TLR4 rs4986790 to severe malaria in this study." (PMID 24312262, 2013). "Furthermore, certain TLR4 variants have been shown to predispose certain individuals to severe malaria." (PMID 23967200, 2013). "Finally, a polymorphism was seen in the TLR4 gene (rs4986790) that was associated with reduced risk for clinical malaria." (PMID 22615793, 2012). "TLR4 encodes an extra-cellular receptor present in the antigen presenting cells (APCs) and perceives the malaria antigens to trigger a complex cascade of downstream signaling events which ultimately culminates into the production of several pro-inflammatory cytokines including IL12 and LTA." (PMID 23071570, 2012).
malaria (continued). "In addition, the risk of severe malaria in children was increased 1.5-fold in the presence of TLR4 Asp299Gly and 2.6-fold with TLR4 Thr399Ile." (PMID 23316245, 2012). "Therefore, the current study was designed to look at the polymorphisms in tlr-4 and tlr-9 genes in Baluchi ethnic groups from south-eastern parts of Iran with unstable and hypoendemic malaria transmission." (PMID 21457584, 2011). "In general, the importance of TLRs in malaria is underlined by the fact that TLR4 polymorphisms can predispose to severe malaria and that polymorphisms in both TLR4 and TLR9 may play a role in the severity of pregnancy associated malaria." (PMID 21483827, 2011). "Indeed, TLR mutations have been shown to play an important role in the outcome of pregnancy associated malaria, and in particular TLR-4 and -9 mutations are associated with increased risk of low birth weight in term infants." (PMID 20074331, 2010). "Interestingly, a recent study has shown a link between polymorphisms in the TLR-4 locus and susceptibility to severe malaria in humans; our data offer a plausible biological explanation for this observation." (PMID 20126448, 2010). "Also, in a recent study of 304 pregnant women infected with P. Falciparum from South Ghana, the D299G allelic variant of TLR4 was associated with a 5-fold increased risk of severe maternal anemia, as a result of ineffective clearance of the malaria parasites." (PMID 18382655, 2008). "However, unlike in the Burundian children, we found MAF of 17.6 % and 10.4 % for TLR4 Asp299Gly and Thr399Ile among our severe malaria sub-group with genotypes containing these alleles further found to increase the risk of severe malaria 3-fold and 8-fold respectively." (PMID 27350800, 2015). "Despite evidence from the HapMap project that the various genotypes of TLR4 Asp299Gly and Thr399Ile SNPs are in circulation among the Yoruba tribe, the roles of these SNPs in influencing susceptibility to clinical and severe malaria remain unknown." (PMID 27350800, 2015). "In the current immunogenetic study, weassessed the TLR4 genotypes formed by the two common single nucleotide polymorphisms(SNPs) (Asp299Gly and Thr399Ile) in the co-segregate state in BaluchiPlasmodium falciparum infected and healthy populations from malaria hypoendemicareas of Iran." (PMID 23862121, 2013). "However, because the frequency of TLR4 Asp299Gly was always low in this study and in those previously reported, it is difficult to draw firm conclusions on the role of this SNP in susceptibility modulation to malaria and disease severity." (PMID 22691414, 2012). "This study aimed to evaluate the association between polymorphisms in TLR1, TLR4, TLR7, TLR8, TLR9 and TIRAP and the clinical manifestations of malaria caused by P. vivax in a population from the Amazon region of Pará, Brazil." (PMID 40963451, 2025). "Here, we expanded those results by linking suppression of HSP70 with TLR2 and TLR4, HSP60, and associated signaling cascades in malaria-infected children with severe anemia." (PMID 39452740, 2024). "Although enhanced TLR4 expression was reported on monocytes of malaria patients, in a mouse model TLR4 expression was much less enhanced than that of other TLRs after infection with P. chabaudi." (PMID 37240201, 2023). "The results herein provide evidence for the association of TLR4 and related genes, ICAM1, IFNGR1, IL13, and IL6, as well as ABO, with the incidence of clinical malaria." (PMID 37287037, 2023). "The TLR4 gene was found to be involved in many metabolic pathways related to legionellosis, toxoplasmosis, malaria, amoebiasis, and leishmaniasis." (PMID 35883364, 2022). "For example, the combination of lipophilic adjuvants and toll-like receptor 4 (TLR4) agonists improves T follicular responses to malaria vaccines in mice." (PMID 36077216, 2022).